PROM1 (prominin 1)
Diseases named in the same sentence as PROM1 in open-access papers (continued):
Sharing a sentence is not in itself a finding about the gene and the disease.
tumor (continued). "The expression of stem-like markers, such as hyaluronic acid receptor (CD44), prominin-1 (CD133), nestin, or sex-determining region Y (SRY)-box 2 (Sox2) in several tumour types led to proposal of the CSC/TIC hypothesis some years ago." (PMID 29890731, 2018). "CD133, also known as prominin-1 or AC133 (a glycoprotein comprising of five transmembrane domains), has been described as a marker of stem cells in several organs and appears to be the CSC marker for a number of tumor types." (PMID 24932297, 2014). "Irrespective of the tumor types, prominin-1 was often detected at the apical membrane of polarized tumor cells that resembled secretory serous and mucous cells as well as intercalated duct cells of normal salivary glands." (PMID 24911657, 2014). "Survival was again longer for the mice implanted with Prom1+ fraction, suggesting that Prom1+ tumor cells are not essential for PDGF-driven proneural GBM growth." (PMID 23637986, 2013). "A trend toward higher levels of expression of ALCAM, CD24, and CD44, but not PROM1, was observed in CXs derived from D61540 when compared with their parental tumor." (PMID 24278200, 2013). "Many types of CSCs, including tumor-initiating cells in brain, kidney, liver, colon and pancreatic carcinomas were isolated and enriched using the cell surface marker CD133, or prominin-1 alone or in combination with some other markers." (PMID 20630067, 2010). "Notably, two of the four patients with PROM1 over-expressing tumors had highly drug-resistant disease and died 11 and 13 months from diagnosis (one with an EWS-FLI1 and one with an EWS-ERG tumor)." (PMID 20346143, 2010). "To determine if over-expression of the PROM1 transcript is indicative of an increased frequency of CD133+ cells we obtained fresh-frozen tumor sections from a PROM1 negative and a PROM1 positive case." (PMID 20346143, 2010). "In order to investigate whether BET inhibition affects the tumor-initiating ability of EPN SC cultures, we assessed the expression of previously defined neural cancer SC markers (PROM1, NES and SOX2) and of the astrocytic marker GFAP in the cells treated with OTX015." (PMID 33668642, 2021). "Thus, we cannot rule out a possibility of PROM1+ DRPs giving rise to tumor cells either directly or through TICs." (PMID 33173221, 2020). "It appears clear that T98G, although originating from GBM, behave quite differently as their capacity to generate tumor-spheres was null in our hands, and neither PROM1 nor ENG expression were induced under hypoxia conditions, as occurred with the rest of GBM cells." (PMID 33396280, 2020). "Not surprisingly, a number of proteins involved in tumor cell dissemination and BBB invasion were also found to associate with BCBM progression, including cathepsin-S, S100A4, RANKL, RANK, Src, HYAL1, HAS2 and prominin-1 (CD133)." (PMID 32110283, 2020). "This situation mirrors that of CD133/PROM1, so we speculate that the apparently low tumor-wide expression of ABCG2 and ICAM4 is because they are robustly expressed only in CD133+ cells, which constitute a minor fraction of the tumor cells." (PMID 23527012, 2013). "The relationship between STAT3-dependent inhibition of autophagy and PROM1 (cytosolic) expression is novel and may provide valuable insights into GBM tumorigenesis and help identify new molecular markers that are predictive of GBM tumor recurrence and chemoresistance." (PMID 40396025, 2022). "Interestingly, the PROM1 expression did not affect a tumor response to the TP therapy." (PMID 35867729, 2022). "In agreement with this hypothesis, higher expression of PTGER4 is observed in the tumour bulk of GBM18 and in the TCGA GBM cohort as compared to GIC18, and a negative correlation was observed between the expression of PTGER4 and PROM1 (CD133), a GIC marker, in the TCGA datasets." (PMID 34675201, 2021). "However, GBM PROM1 negative cells can also contribute to tumor propagation." (PMID 25184684, 2014).
tumor (continued). "Like the i-As (III)-exposed HRTPT cells, the PROM1-expressing RCC cells did not form tumors upon xenotransplantation, but when co-transplanted with RCC cells, they enhanced tumor engraftment, vascularization, and growth." (PMID 40558504, 2025). "This analysis led to the identification of the genes CX3CL1, CCL28, PROM1, and KLK5, which were highly expressed in the boundary cells and not in tumor cells, myoepithelial cells or any other colocalized cell type." (PMID 38114474, 2023). "In the Prom1+ cells, the dominant cell type was HCC cells, accounting for about 95% throughout the disease development, suggesting that the Prom1+ cells did not transdifferentiate into other lineages in this chronic HCC model and they were the expanding epithelial tumor cells during HCC progression." (PMID 36766817, 2023). "Metastatic fibroblasts could potentially be tumor epithelial cells that have fully transformed (as many of the tumor epithelial expressed genes imply), but metastatic fibroblasts we observed do not express PROM1/CD133, a well described cancer stem cell marker." (PMID 30383866, 2018). "Experimental design: Eight novel candidate markers, COL4A6, CYBA, TCAF1 (FAM115A), HLF, LINC01341 (LOC149134), LRRC4, PROM1, and RHCG, were selected from Illumina Infinium HumanMethylation450 BeadChip analysis of 21 tumor (T) and 21 non-malignant (NM) prostate specimens." (PMID 28052017, 2017).
cancer (2,374 papers, 2006 to 2026). A tumor composed of atypical neoplastic, often pleomorphic cells that invade other tissues. "Loss of MTAP has been associated with enhanced cancer cell stemness in GBM as demonstrated by increased expression of prominin-1 (PROM1), also known as CD133, further elevating the tumorigenicity of these cells." (PMID 41439984, 2025). "The Prominin-1 (Prom1) gene encodes a transmembrane glycoprotein, which is widely recognized as an antigenic marker for stem cells and cancer stem cells." (PMID 39513868, 2024). "CD133 (prominin 1) is another surface antigen not only associated with cancer stem cells but also found on the surface of hematopoietic stem cells and neural stem cells." (PMID 38455073, 2024). "Prom1 marks a stem compartment of progenitor cells that replenish tissue and cause cancers of the GI tract when mutated." (PMID 37748809, 2023). "CD133/Prom1 expression has been used as a marker to identify adult stem cell populations in various organs and often associated with cancer cells that have stem-like properties." (PMID 37605939, 2023). "CD133 (prominin 1) is widely viewed as a cancer stem cell marker in association with drug resistance and cancer recurrence." (PMID 37846866, 2023). "PROM1 was involved in regulations of drug resistance and metastasis in various cancer cells, and the expression and mutation of this gene were associated with poor prognosis in non-small lung cancer." (PMID 36430822, 2022). "Although most cancers are removed through cancer therapy, only a small number of surviving PROM1-positive cells can proliferate and cause cancer to recur." (PMID 36266314, 2022). "AFP and PROM1 are accepted markers for cancer stem cells in the liver and are associated with recurrence, metastasis and chemoresistance in HCC." (PMID 34830835, 2021). "In cancer, some studies suggest that prominin-1 is also associated with exosomes as demonstrated in blood stem cells." (PMID 34476215, 2021). "The database was first queried for PROM1 gene mutations in 56,250 samples from 215 studies that covered the entire set of available cancers." (PMID 31164716, 2020). "In H19-deficient cells, expression of cancer stem-cell markers Prominin-1 (CD133), homeobox protein NANOG (NANOG), Octamer-binding transcription factor 4 (Oct4), and Sox2 are downregulated." (PMID 32650527, 2020). "Specifically, PROM1 mutations mainly occurred in uterine pan-cancer and consisted of several frame-shift insertion or deletion mutations in a hotspot at position p.N566Ifs*29/Kfs*2 in the prominin domain." (PMID 31164716, 2020). "Considering these findings we sought to further explore the normal and cancer expression pattern and lineage associations of Prominin-1 in human and mouse brain." (PMID 25184684, 2014). "Cancers that express the basal CK-5 or the cell stemness-linked proteins prominin-1 or nestin are associated with the brain as the first site of distant recurrence." (PMID 21914172, 2011). "We will further discuss the molecular and cellular characteristics of prominin-1, notably those that have a direct effect on the release of prominin-1+ EVs, a process that might be directly implicated in donor cell reprogramming of stem and cancer stem cells." (PMID 39881297, 2025). "The interception of prominosomes-mediated intercellular crosstalk, particularly in cancer, where EV-associated prominin-1 and other cargoes can induce proliferation, EMT and cancer cell invasion, could be of interest." (PMID 39881297, 2025). "In addition to the upregulation of the PROM1 gene, which encodes the common marker for cancer stem cells CD133, the ISY1-RAB43 gene, proposed as a novel marker for cancer stem cells, was also upregulated." (PMID 40724830, 2025). "PROM1 (also known as CD133) is a suggested marker for intestinal stem cells that are susceptible to neoplastic transformation and is recognized as a stem cell marker in several tissues and in many cancers." (PMID 24714516, 2014).
cancer (continued). "CD133 (also known as AC133 or prominin-1) is a cell-surface glycoprotein comprising five transmembrane domains and two large glycosylated extracellular loops and has commonly been associated with subpopulations of cells with highly tumorigenic capacity in several cancers including HNSCC." (PMID 26880935, 2016). "Considering the link between stem cell differentiation and the loss of prominin-1 via asymmetric cell division and/or its release in association with membrane vesicles, new perspectives in the biology of stem and cancer stem cells might emerge." (PMID 24911657, 2014). "Anti-CD133/PROM1 (cancer marker) and anti-fibroblast (clone TE-7) antibodies were used to demonstrate a lack of contaminating cells." (PMID 42182494, 2026). "The same rationale can be applied to saliva-derived prominin-1+/-2+ EVs to monitor salivary gland stem cell transplantation or cancer." (PMID 39881297, 2025). "Indeed, our GO enrichment analysis further showed that PROM1 appears to be associated with kidney development and epithelial cell differentiation, supporting its multifaceted involvement in both normal tissue development and potentially aberrant processes in cancer." (PMID 40650074, 2025). "Given the diversity of cells expressing prominin-1 (stem cells, terminally differentiated cells and cancer cells) and the variety of physiological fluids containing prominosomes, various functions can be attributed to them." (PMID 39881297, 2025). "In progenitor cells, as seen in the neuronal system, the release of the stem (cancer stem) cell biomarker prominin-1 (CD133) via ectosomes derived from the ciliary tip, among other sources, is apparently linked to the differentiation process." (PMID 41039495, 2025). "Prominin 1 (PROM1) is considered a biomarker for cancer stem cells, with an unclear biological role, negatively associated with prognosis." (PMID 40804837, 2025). "CD133, also known as Prominin-1, is a five-transmembrane glycoprotein that is critical in several cancer-related processes, including tumorigenesis, metastasis, and resistance to chemotherapy and radiotherapy." (PMID 39316249, 2025). "CD133 (prominin-1) is a membrane glycoprotein expressed in CSCs of many cancer types, and it is localized in membrane protrusions of the apical polarity of epithelial cells." (PMID 40332380, 2025). "Beyond its presence on the cell surface, prominin-1 has been detected in intracellular compartments such as endosomes and the Golgi apparatus of various cancer and non-cancer cell lines (e.g., Caco-2, Huh-7, SK-N-DZ, FEMX-I, ARPE-19 cells), and tissue samples." (PMID 39881297, 2025). "Originally described as a novel cell surface biomarker for neural and hematopoietic stem and progenitor cells (HSPCs), prominin-1 has attracted attention in oncology as it highlights cancer cells with stem cell properties." (PMID 39881297, 2025). "CD133, often referred to as prominin-1, is the predominant cell surface antigen employed for identifying and separating cancer stem cells (CSCs) in many types of solid tumors, such as those found in the brain, colon, pancreas, prostate, lung, and liver." (PMID 41155569, 2025). "In line with the complex role of PROM1 in ccRCC, its involvement in other cancers also appears to be context dependent." (PMID 40650074, 2025). "In most tissues, Prominin-1 is partially co-expressed with cancer markers such as carcinoembryonic antigen (CEA) and mucin 1 (MUC1)." (PMID 39409917, 2024). "One of the most studied immunohistochemical markers is CD133 (Prominin-1), a transmembrane glycoprotein present on the surface of cancer stem cells." (PMID 39459448, 2024). "Among the top 50 genes most significantly downregulated by MP1, we identified PROM1 (CD133, neural stem cell) as one of the most cancer relevant genes, particularly considering its crucial roles in neurodevelopment and Group 3 MB tumorigenesis." (PMID 38200580, 2024).
cancer (continued). "In particular, it makes cells expressing the cancer stem cell marker glycoprotein prominin-1 (CD133) highly resistant to proliferative and metastatic potential." (PMID 38367174, 2024). "CD133 (Prominin-1), a glycoprotein often expressed on stem-like cells from many cancer types, has been proposed as a CSC marker in MPNSTs." (PMID 39518076, 2024). "Within the TCGA HGSOC cohort, GNAS expression was significantly correlated with expression of the EMT markers Vimentin and N-cadherin, and the cancer cell stemness marker PROM1." (PMID 38097740, 2024). "Labeled Prom1+ cells exhibit increasing tumorigenicity in 3D culture and allotransplantation, as well as potential to form cancers of differential lineages on transplantation." (PMID 38030644, 2023). "CD133/1 (prominin-1) is highly expressed in hematopoietic progenitor cells, cancer stem cells, neural stem cells, and others." (PMID 37622115, 2023). "PROM1 encodes a transmembrane glycoprotein (i.e., CD133) commonly regarded as a cancer stem cell marker and reported to be an important target of KMT2A::AFF1." (PMID 37740239, 2023). "We found higher levels of epithelial stem cell/cancer stem cell markers (e.g., Lgr5, Axin2, Cd44, Prom1/CD133) in the tumoroids derived from ApcMin/+ WT as compared with ApcMin/+ Stat2−/− mice." (PMID 38001683, 2023). "Various genes, such as CD44, CD117, Prom-1 (also known as CD133), ALDH, and NANOG, are associated with cancer stemness." (PMID 36982993, 2023). "CD133, also called prominin-1, is widely known as a cancer stem cell marker, and its high expression correlates with a poor prognosis in many cancers." (PMID 36899954, 2023). "Prominin-1, a lipid raft protein, is required for maintaining cancer stem cell properties in hepatocarcinoma cell lines, but its physiological roles in the liver have not been well studied." (PMID 36266314, 2022). "PROM1 has been studied as one of the most widely used cancer stem cell (CSC) markers in various human tumors, including the liver." (PMID 36266314, 2022). "PROM1 is an important surface marker of normal and cancer stem cells and has several binding partners, such as Actin, Radixin, PI3K, and HDAC623,34–36." (PMID 36038590, 2022). "Pentaspan membrane glycoprotein CD133 (Prominin-1), a marker of cancer stemness, can be used to predict the poor prognosis of patients with many different types of tumors." (PMID 36076996, 2022). "CD24 in combination with CD44 and/or CD133 (PROM1) has been highlighted as cancer stem cell markers (in combination with NANOG, OCT3/4, and SOX2), and a cell‐type‐dependent correlation of CD24 to the chemokine receptor CD184 (CXCR4) has been shown." (PMID 34293822, 2022). "CD133 is a surface glycoprotein expressed by neural stem cells encoded by PROM1, and is a marker of therapy-resistant, tumorigenic cells in cancer stem cell models." (PMID 36333778, 2022). "The cancer stem cell biomarker, Prominin-1 (Prom1) is upregulated in response to mitochondrial dysfunction suggesting that Prom1 expression is regulated by bioenergetic stresses." (PMID 35715869, 2022). "Meanwhile, CD133, also known as prominin-1, is one of the most used biomarkers for the isolation of cancer stem cells (CSCs)." (PMID 33869033, 2021). "The best polygenetic model included DIRC3_rs6759952, GAP43_rs13059137, NRG1_rs7834206, PROM1_rs72616195, LRP1B_rs1369535, and LOC100507065_rs11175834, tumorigenesis and cancer cell differentiation-related genes." (PMID 33805984, 2021). "Targeting prominin-1-expressing cells in relation to signaling cascades for cancer therapy has indeed been the concern of many over the past decade." (PMID 34476215, 2021). "ESR1-depleted recurrences harbored shared transcriptional remodeling events including upregulation of PROM1 and other basal cancer markers." (PMID 33407744, 2021).